SMAD7 (SMAD family member 7)
Diseases named in the same sentence as SMAD7 in open-access papers (continued):
Sharing a sentence is not in itself a finding about the gene and the disease.
kidney diseases (20 papers, 2011 to 2023). "Smad7 has been shown to be a downstream target of several miRNAs previously associated with DN and other renal diseases." (PMID 32215042, 2020). "This assumption is supported by the findings that Smad7 overexpression in different models of renal diseases exhibit significantly inflammation suppression." (PMID 31455237, 2019). "Recently, TGF-β/Smad7 has been demonstrated to be important not only in kidney diseases, but also in cardiac diseases." (PMID 28881850, 2017). "Smad7, one of the I-Smads, has been shown to inhibit fibrosis and inflammation in many kidney diseases, however, study has shown that decreased Smad7 expression contributed to cardiac fibrosis in the pathogenesis of cardiac fibrosis in the post-MI heart." (PMID 28881850, 2017). "Accumulated evidence shows that targeting Smad3 by overexpressing renal Smad7 produces inhibitory effects on both renal inflammation and fibrosis in a variety of kidney disease models." (PMID 25852569, 2015). "Transcription factors that are targeted by Sirt1 and also play a significant role in the pathophysiology of kidney disease include Smad7, HIF-2α, and Stat3." (PMID 21858169, 2011). "Tying together these findings with previous studies on other renal disease models highlighting the capability of Smad7 overexpression to attenuate kidney inflammation and fibrosis, Smad7 could play a protective role in the pathogenesis of chronic AAN." (PMID 30893813, 2019). "Thus, rebalancing Smad3/Smad7 signaling may be a better therapeutic approach for combating kidney diseases." (PMID 35541902, 2022). "Thus rebalancing Smad3/Smad7 signaling by either inhibiting Smad3 and/or activating Smad7 may be a better approach for the development of effective and specific therapy for kidney diseases." (PMID 35541902, 2022). "This notion is also supported by the results from different mouse models of kidney diseases induced in mice lacking Smad3 or Smad7 or having conditional knockout (KO) for Smad2 or overexpressing renal Smad7." (PMID 24550986, 2014). "All these studies suggest that specific targeting the downstream TGF-β/Smad3 signaling pathway by overexpression of Smad7, rather than blocking the general effect of TGF-β1 with neutralizing antibodies, may represent a specific and effective therapeutic strategy for kidney disease." (PMID 23301086, 2013).
inflammation (10 papers, 2013 to 2021). Aberrant reaction of the microcirculation characterized by movement of fluid and leukocytes from the blood into extravascular tissues. "We then tested a hypothesis that the protection of Smad3 KO‐db/db mice from cardiac inflammation may be associated with the inactivation of NF‐κB signalling by blocking Smurf2‐mediated ubiquitin degradation of cardiac Smad7." (PMID 33733577, 2021). "In summary, we provided in vitro evidence that miR-216a promotes endothelial inflammation and enhances the adhesion ability of monocytes to endothelial cells by directly targeting the Smad7/IκBα pathway." (PMID 33282009, 2020). "Our findings extended the knowledge of miR-216a on endothelial inflammation involving Smad7/IκBα pathway in vitro and in vivo." (PMID 33282009, 2020). "We have previously reported that Smad7 functions as an inhibitor of NF-κB signaling to block NF-κB-dependent renal inflammation in vitro and in vivo." (PMID 25883225, 2015). "In the present study, the finding that disruption of Smad7 enhanced further NF-κB activation added new evidence that Smad7 protects against Ang II-induced cardiac inflammation through inhibition of the NF-κB pathway." (PMID 23894614, 2013). "This new finding suggests that enhanced ANG II-induced Sp1 pathway may be an additional mechanism by which mice lacking Smad7 were promoted ANG II-mediated renal inflammation and fibrosis." (PMID 23301086, 2013).
cardiac disease (2 papers, 2013 to 2023). "Hypertensive cardiac disease was induced in Smad7 gene knockout (KO) and wild-type (WT) mice by subcutaneous infusion of Ang II (1.46 mg/kg/day) for 28 days." (PMID 23894614, 2013).
diseases of the digestive system (1 paper, 2016). "Genome-wide association studies (GWAS) have identified three loci at 18q21 (rs4939827, rs7240004, and rs7229639), which maps to SMAD7 loci, were associated with risk of diseases of the digestive system." (PMID 26989026, 2016).
immune diseases (1 paper, 2021). "The role of Smad7 in immune diseases has been studied extensively in the past few years due to the scientific advancements in the field." (PMID 34059951, 2021). "Smad7 participates in the differentiation of T cells and promotes activation of immune cells such as B cells and DCs by negatively regulating the TGF-β pathway and may thereby mediate the progression of immune diseases." (PMID 34059951, 2021).
intestinal disorder (1 paper, 2021). A non-neoplastic or neoplastic disorder that affects the small or large intestine. "Furthermore, the broad variety of intestinal disorders in which a role of Smad7 has been hypothesized and/or demonstrated opens multiple possibilities about future therapeutic approaches." (PMID 33920230, 2021).
musculoskeletal diseases (1 paper, 2024). "SMAD7 shows the strongest association with musculoskeletal diseases, with CCNB1 in second place." (PMID 39840278, 2024).
skeletal dysplasia (1 paper, 2020). Any Mendelian diseases that affects growth and development of the skeleton. "We are only aware of one other skeletal dysplasia reported in association with an inhibitory SMAD (which include SMAD6 and SMAD7)." (PMID 31525280, 2020).
SMAD7 also shares sentences with these, for which no sentence is quoted: kidney (6 papers); renal cell carcinoma (4); leukemia (3); lymph node metastasis (3); neuroblastoma (3); Peyronie disease (3); pulmonary hypertension (3); cholangiocarcinoma (2); crescentic glomerulonephritis (2); depression (2); Insulin resistance (2); parasite infection (2); Sepsis (2); systemic lupus erythematosus (2); type 1 diabetes (2); acute myocardial infarction (1); adenocarcinoma (1); allergic disease (1); alveolitis (1); anaplastic thyroid carcinoma (1); aortic stenosis (1); B-Cell CLL (1); B-cell lymphoma (1); basal cell carcinoma (1); benign papillomas (1); bowel obstruction (1); cardiac ischemia (1); cerebral atherosclerosis (1); chronic myeloid leukemia (1); chronic obstructive pulmonary disease (1).
A further 60 diseases each share a sentence with SMAD7 in 1 paper.